F10 (coagulation factor X)
Diseases named in the same sentence as F10 in open-access papers:
F10 is named in the same sentence as 218 diseases in open-access papers, as found by Europe PMC text mining. Sharing a sentence is not in itself a finding about the gene and the disease. The quoted sentences say what the papers report.
atrial fibrillation (200 papers, 2009 to 2026). A disorder characterized by an electrocardiographic finding of a supraventricular arrhythmia characterized by the replacement of consistent P waves by rapid oscillations or fibrillatory waves that vary in size, shape and timing and are accompanied by an irregular ventricular response. "Recently, as an alternatively to warfarin, anticoagulant therapy directly targeting activated coagulation factor X (FXa) has been established as a treatment strategy for atrial fibrillation." (PMID 37268884, 2023). "One patient in the LLR group experienced hemorrhage after receiving an anticoagulant, a coagulation factor X inhibitor, for cardiovascular disease (ischemic heart disease, atrial fibrillation, and installed pacemaker) early in the postoperative period." (PMID 35197022, 2022). "Direct targeting of activated coagulation factor X (FXa) is a relatively new strategy for the treatment of atrial fibrillation and deep vein thrombosis." (PMID 29215061, 2017). "The rational discovery of new peptidomimetic inhibitors of the coagulation factor Xa (fXa) could help set more effective therapeutic options (to prevent atrial fibrillation)." (PMID 35807514, 2022). "Direct oral anticoagulants (DOAC), drugs directly inhibiting thrombin (dabigatran) or activated coagulation factor X (apixaban, edoxaban and rivaroxaban), are currently the drugs of choice for the pharmacological prevention of stroke or systemic embolism in patients with atrial fibrillation (AF)." (PMID 36362597, 2022).
deep vein thrombosis (75 papers, 2011 to 2026). "Abnormal coagulation factor X concentration, thrombosis with thrombocytopenia syndrome, and incision site hematoma had the strongest signals." (PMID 41671250, 2026). "Edoxaban directly inhibits the activated coagulation factor X (FXa), and has been used as an anti-coagulant for cardioembolic infarction, deep vein thrombosis, and pulmonary embolism." (PMID 40457359, 2025).
venous thromboembolism (60 papers, 2009 to 2026). Occlusion of the lumen of a vein by a thrombus that has migrated from a distal site via the blood stream. "Prothrombin, coagulation factor X, coagulation factor VII and tissue factor exhibited vital modulation function in hypercoagulability state and venous thromboembolism of COPD17,37." (PMID 31530860, 2019).
COVID-19 (47 papers, 2020 to 2025). A disease caused by infection with severe acute respiratory syndrome coronavirus 2. "In this review article, we will discuss the potential role of coagulation factor Xa (FXa) in the pathophysiology of COVID-19." (PMID 33043235, 2020).
Thromboembolism (26 papers, 2015 to 2025). The formation of a blood clot inside a blood vessel that subsequently travels through the blood stream from the site where it formed to another location in the body, generally leading to vascular occlusion at the distant site. "It has been shown that quercetin inhibited thrombin and coagulation factor Xa (FXa) activity in a thrombin-induced acute thromboembolism model in mice, thereby inhibiting thrombus formation." (PMID 40969941, 2025).
coagulopathy (17 papers, 2013 to 2023). "Furthermore, the upregulation of miR-24-3p (log2 fold change = 1.79) observed here in the animals subjected to THS (p < 0.001) concurs with the overexpression of miR-24-3p reported in trauma patients associated with trauma-induced coagulopathy by preventing the production of coagulation Factor X." (PMID 33072784, 2020).
hemophilia (13 papers, 2018 to 2026). Hemophilia is a genetic disorder characterized by spontaneous hemorrhage or prolonged bleeding due to factor VIII or IX deficiency. "Coagulation factor X plays a critical role in the downstream of blood coagulation cascade, which could serve as a bypassing agent for hemophilia therapy." (PMID 33783994, 2021).
Hypertension (10 papers, 2021 to 2025). The presence of chronic increased pressure in the systemic arterial system. "Moreover, our findings underscore the critical role of differentially expressed genes, particularly FOXD3, F10, and SLC12A5, in the pathogenesis of both hypertension and thyroid cancer." (PMID 40785195, 2025).
Sepsis (8 papers, 2008 to 2025). Sepsis is defined as life-threatening organ dysfunction caused by a dysregulated host response to infection. "Similarly, three genes encoding fibrinogen alpha (Fga), beta (Fgb), and gamma chains (Fgg), and Coagulation Factor X (F10) were increased by sepsis in the lungs and kidneys." (PMID 37638006, 2023).
AL amyloidosis (7 papers, 2012 to 2025). AL Amyloidosis is a plasma cell disorder characterized by the aggregation and deposition of insoluble amyloid fibrils derived from misfolding of monoclonal immunoglobulin light chains usually produced by a plasma cell tumor. "Additional red flags in the diagnosis of AL amyloidosis are coagulation factor X deficiency, highly specific to AL amyloidosis but uncommon, sometimes favoring the development of “racoon eyes” (i.e., periorbital ecchymoses), and macroglossia." (PMID 35326711, 2022).
melanoma (7 papers, 2013 to 2024). A malignant, usually aggressive tumor composed of atypical, neoplastic melanocytes. "Herein, we examined the contribution of a hypercoagulative state through the administration of intravenous Coagulation Factor Xa (FXa), on the growth of solid human tumors and the experimental metastasis of the B16F10 melanoma in mouse models." (PMID 31382462, 2019).
glioblastoma (5 papers, 2018 to 2025). The most malignant astrocytic tumor (WHO grade IV). "Specifically, glioblastoma cells have been shown to express and secrete coagulation factor X (FX), which actively promotes thrombin generation, further contributing to the prothrombotic state in these patients." (PMID 40283046, 2025). "More importantly, the expression of F10 mRNA was progressively reduced in U87 cells that were cultured over time in the condition of oxygen and glucose deprivation, which is often found in the microenvironment of the glioblastoma tissue niche." (PMID 40149552, 2025).
hemophilia B (3 papers, 2014 to 2023). Hemophilia B is a form of hemophilia characterized by spontaneous or prolonged hemorrhages due to factor IX deficiency. "Platelet-stored activated blood coagulation factor X (FXa) has great potential in the gene therapy of hemophilia B (HB)." (PMID 37779119, 2023).
liver diseases (3 papers, 2022 to 2024). "In liver diseases, coagulation factor Xa (FXa)-PAR-2 signaling promotes hepatic inflammation and liver fibrosis." (PMID 38748746, 2024).
nephrotic syndrome (3 papers, 2025 to 2026). A collection of symptoms that include severe edema, proteinuria, and hypoalbuminemia; it is indicative of renal dysfunction. "Therefore, it is conceivable that plasmin might be one of the drivers of C3 activation in nephrotic syndrome, although other proteases capable of activating C3 might act in concert and have been reported to be excreted in nephrotic urine such as thrombin, coagulation factor X or plasma kallikrein." (PMID 40909784, 2025).
astrocytomas (1 paper, 2016). "Our data have verified four new hypomethylated genes, F10, POTEH, LMO3 and CPEB1, and their prognostic values in astrocytomas." (PMID 26701852, 2016).
hypothyroidism (1 paper, 2024). Abnormally low levels of thyroid hormone. "Those with hypothyroidism had significantly reduced activity of coagulation factor X [by −30% (95% CI −47 to −13)] and protein S [by −27% (95% CI −41 to −13)] compared with euthyroid NS individuals." (PMID 39323731, 2024).
MRSA pneumonia (1 paper, 2013). "This may explain why coagulation factor X (F10) was up-regulated during MRSA pneumonia." (PMID 23826353, 2013).
proctitis (1 paper, 2024). An inflammatory process affecting the anus. "And it is worth noting that uncommon but significantly ADE signals, such as “Coagulation factor X level increased”, “Basal ganglia haematoma”, and “Proctitis haemorrhagic” also should be concentrated on." (PMID 39309013, 2024). "Moreover, uncommon but significantly suspected AE signals, such as “Coagulation factor X level increased”, “Basal ganglia haematoma”, and “Proctitis haemorrhagic” were observed." (PMID 39309013, 2024). "Focus also should be placed on suspected AEs with strong signals not common reported, such as “Coagulation factor X level increased”, “Basal ganglia haematoma”, and “Proctitis haemorrhagic”." (PMID 39309013, 2024).
cancer (112 papers, 2006 to 2026). A tumor composed of atypical neoplastic, often pleomorphic cells that invade other tissues. "Coagulation factor X (FX), a coagulation protease encoded by the gene F10, has garnered attention in recent cancer research due to its involvement in tumor progression, including PTC." (PMID 38793106, 2024). "Emerging evidence suggests coagulation factor X, encoded by the F10 gene, has a potential role in inhibiting cancer cell migration." (PMID 38793106, 2024). "Rivaroxaban; is a small molecule that inhibits coagulation factor X (FX) activation and enhances anti-cancer immune response by increasing infiltration of dendritic cells and cytotoxic T cells at the tumor region." (PMID 37280670, 2023). "On the other hand, elevating of F10 protein was observed in clinical cancer cases as well as cell lines." (PMID 27409342, 2016). "Coagulation Factor X (F10) is a serine protease that can be activated by cancer procoagulant (CP), a cysteine protease produced by malignant and embryonic tissues." (PMID 20027305, 2009). "Our analysis revealed 9 shared genes, with UBE2C, POLQ, RAD51, and HOXB7 being up-regulated and EDNRB, GPD1L, F10, SORBS2, and CXCL12 down-regulated in both cancers." (PMID 41790655, 2026). "Indeed, our findings identified altered glycosylation of two additional proteins not yet considered in the cancer coagulome, namely, thrombin (THRB) and coagulation factor X (FA10), which should be evaluated for inclusion in the coagulome." (PMID 37147936, 2023).
tumor (86 papers, 1979 to 2026). "Nowadays, these strategies might be even more effective for tumor targeting after systemic delivery than the incorporation of mutations in the Ad5 hexon protein to abolish binding of the capsid to coagulation factor X." (PMID 25714032, 2015). "Preclinical animal studies have suggested that myeloid cell–synthesized coagulation factor X dampens antitumor immunity and that rivaroxaban, a direct factor Xa inhibitor, can be used to promote tumor immunity." (PMID 38950074, 2024). "After that, the study verified that LncCASC2c acts as an inhibitor for coagulation factor X, therefore LncCASC2c is considered as a tumour-suppressor agent (Ref." (PMID 39320855, 2024). "Coagulation factor X exhibits potent chemotactic activity, recruiting and promoting M2 macrophage polarization and regulation of tumor growth." (PMID 35151325, 2022). "Recent studies have found that the coagulation factor Xa (FXa) synthesized by monocytes and macrophages can promote tumor metastasis and immune escape by activating PAR-2." (PMID 36105100, 2022). "Tumour‐bearing mice exhibited a threefold increase in coagulation factor X (FX, F10) expression in leucocytes compared with tumour‐free controls." (PMID 29930175, 2018). "While transcriptionally targeted to vascular endothelium with a tumor microvessel bias, this vector required warfarin depletion of the coagulation Factor X for significant tumor vascular delivery." (PMID 28103576, 2017). "The reporter peptide CP-RP comprises the cleavage site WKPYDAAD that is part of the coagulation factor X and is preferably cleaved in serum specimens of tumor patients." (PMID 22682081, 2012). "It is concluded that cells from some experimental tumours have the capacity to activate Coagulation Factor X directly." (PMID 573131, 1979). "For example, myeloid cells of the tumor microenvironment (TME) secrete the coagulation factor Xa, which acts as a regulator of immune cell activation and contributes to tumor immune evasion, and factor Xa inhibitor (rivaroxaban) usage increases the anti-tumor response of mice to ICI therapy." (PMID 39487855, 2024). "Observations in murine systems suggested that coagulation factor Xa impedes anti-tumor immunity and that the oral FXa-inhibitor (FXa-i) rivaroxaban might synergize with ICI." (PMID 34680252, 2021). "Tumor cells could express tissue factor which consequently interacts with coagulation factor VII (FVII) and coagulation factor X (FX) to generates thrombin to enhance tumor progression." (PMID 23861980, 2013). "Human species C adenovirus (HAdv-C5) is bound by immunoglobulin M (IgM) and coagulation factor X (FX) in the blood when delivered intravenously, leading to the sequestration of OVs in liver-resident macrophages (Kupffer cells), limiting their tumor targeting and leading to hepatotoxicity." (PMID 37993941, 2023). "In addition to tumor cells increasing their survival by thrombin generation, the activation of protease-activated receptors (PAR), and specifically PAR2 via cancer cell-expressed TF and coagulation factor VIIa or coagulation factor Xa (FXa), directly contribute to tumor progression." (PMID 34680252, 2021). "Coagulation factor X performs its' function through increasing the phosphorylation and activation of ERK1/2 (ERK can also enhance the angiogenesis of the tumour) and AKT in macrophages." (PMID 39320855, 2024). "Notably, the genes identified in our study—FOXD3, F10, and SLC12A5—may also participate in these IRS‐mediated inflammatory pathways in other tumor types." (PMID 40785195, 2025).
infection (25 papers, 2010 to 2025). The state of being infected such as from the introduction of a foreign agent such as serum, vaccine, antigenic substance or organism. "Third, unlike fibrin glue made from nonautologous blood products, autologous fibrin glue contains coagulation factor X, fibronectin, and other adhesive glycoproteins that can improve wound status rapidly, thereby decreasing the risk of infection." (PMID 29686700, 2018). "Enhanced infection correlates with increased cell binding, which differs mechanistically from that of coagulation factor X-mediated binding, as it remains unaffected by the removal of heparan sulfate." (PMID 40826223, 2025). "For example, HAdV-5C has been shown to recruit and hi-jack coagulation factor X (FX) for infection of hepatocytes, which not only enhances infection but also controls the tropism by directing the virus to the liver." (PMID 38323814, 2024). "In this study, three fibrinogen chains (Fga, Fgb and Fgg) were up-regulated in two L. monocytogenes infections, while coagulation factor X (F10) and C3 were up-regulated only in the L. monocytogenes M7 infection group." (PMID 35682909, 2022). "The phosphorylation level of coagulation factor X was reduced by the CDRV infection and was induced by the DNRV infection." (PMID 32943705, 2020). "In vivo, the infection of liver cells is CAR-independent; instead, it depends on AdV hexon binding to the blood coagulation factor X (fX)." (PMID 39682467, 2024). "Two important serine protease system-related proteins, coagulation factor X and fibrinogen α-chain, were identified as phosphorylated proteins, suggesting an involvement of blood coagulation under the C/NDRV infections." (PMID 32943705, 2020). "The phosphorylation levels of coagulation factor X and fibrinogen α chain were changed, suggesting an enhancement of blood coagulation under the C/NDRV infections." (PMID 32943705, 2020). "Coagulation factor Xa (fXa) and thrombin (thr) are widely expressed in pulmonary tissues, where they may catalyze, together with the transmembrane serine protease 2 (TMPRSS2), the coronaviruses spike protein (SP) cleavage and activation, thus enhancing the SP binding to ACE2 and cell infection." (PMID 36016352, 2022). "However, Ad11, another group B adenovirus, induced significantly lower liver toxicity in animals in comparison to Ad5, maybe due to the lack of interaction of Ad11 with coagulation factor X and the consequent absence of hepatocyte infection." (PMID 27203670, 2016).
kidney disease (3 papers, 2019 to 2021). "Edoxaban, an activated blood coagulation factor Xa (FXa) inhibitor, ameliorates kidney disease by suppressing inflammation and tissue fibrosis in animal models." (PMID 31450643, 2019).
F10 also shares sentences with these, for which no sentence is quoted: Stroke (171 papers); thrombosis (43); pulmonary embolism (26); hypercoagulability (25); atherosclerosis (24); hemophilia A (22); intracranial hemorrhage (22); myocardial infarction (20); ischemic stroke (16); coronary artery disease (14); diabetes (14); intracerebral hemorrhage (14); bleeding disorders (13); breast carcinoma (12); cardiovascular disease (11); peripheral arterial disease (11); renal failure (10); thrombotic disease (10); acute coronary syndrome (9); chronic kidney disease (9); factor deficiency (9); heart failure (8); Obesity (8); hematoma (7); Lupus (7); Thrombocytopenia (7); antiphospholipid syndrome (6); antithrombin deficiency (6); hemorrhage (6); thrombophilia (6).
A further 165 diseases each share a sentence with F10 in 6 papers or fewer.